HCG15 (HLA complex group 15)
Synonyms: dJ25J6.6; dJ25J6.7; HCG16
Gene: Long non-coding RNA gene on chromosome 6 (28,984,724 to 29,007,931, forward strand). Ensembl gene ENSG00000227214.
Gene Ontology:
Molecular function: triplet codon-amino acid adaptor activity
Biological process: translation
Diseases named in the same sentence as HCG15 in open-access papers:
HCG15 is named in the same sentence as 3 diseases in open-access papers, as found by Europe PMC text mining. Sharing a sentence is not in itself a finding about the gene and the disease. The quoted sentences say what the papers report.
glioma (4 papers, 2021 to 2025). A benign or malignant brain and spinal cord tumor that arises from glial cells (astrocytes, oligodendrocytes, ependymal cells). "It has been reported that PABPC5, a protein involved in mRNA stability, binds to HCG15, increasing its levels within glioma cells." (PMID 40277941, 2025). "HCG15, AC007950.2, PTPRN2-AS1, LEF1-AS1, AC021739.2, ARHGAP42-AS1, and LINC01571 were found to be highly expressed in glioma tissues, while TRHDE-AS1 and AC008915.2 were highly expressed in normal cells." (PMID 37101543, 2023). "HCG15, AC007950.2, PTPRN2-AS1, LEF1-AS1, AC021739.2, ARHGAP42-AS1, and LINC01571 were highly expressed in glioma tissues." (PMID 37101543, 2023). "Finally, another important lncRNA in glioma development is HCG15, which participates in the PABPC5/HCG15/ZNF331 feedback loop regulating VM by influencing key protein expression." (PMID 40277941, 2025). "In addition, in the regulation of glioma formation, the PABPC5/HCG15/ZNF331 feedback loop involving HCG15 exerted a significant function, giving a novel target for glioma therapy." (PMID 36189204, 2022). "Similarly, in glioma, SMD is enhanced due to the upregulation of the lncRNA HCG15 that is stabilizes by the binding of PABPC5." (PMID 35008641, 2021).
hepatocellular carcinoma (1 paper, 2023). A malignant tumor that arises from hepatocytes. "HCG15 (human leukocyte antigen complex group 15) facilitates proliferation and invasion by enhancing ZNF641 transcription in hepatocellular carcinoma." (PMID 37101543, 2023).
cancer (1 paper, 2022). A tumor composed of atypical neoplastic, often pleomorphic cells that invade other tissues. "As for the five key CRLs, numerous studies explored the LINC01515 function and HCG15 function in cancer." (PMID 36189204, 2022).